STAT3 (signal transducer and activator of transcription 3)
Diseases named in the same sentence as STAT3 in open-access papers (continued):
Sharing a sentence is not in itself a finding about the gene and the disease.
glioma (continued). "Our present findings confirm that KIAA0247 expression is frequently decreased in glioma tissue, KIAA0247 overexpression inhibits cell growth and angiogenesis and promotes apoptosis in vitro and in vivo via inhibition of AKT and STAT3 signaling." (PMID 27893430, 2016). "As shown by HE staining, the U251 xenografts grew in a more compact manner and were more homogeneous compared with glioma specimens; however, IL6, STAT3 and p-STAT3, LC3B, and HIF1A staining was essentially similar." (PMID 27163161, 2016). "SR-A1 deletion in BMDMs increased this effect, suggesting that STAT3 and STAT6 signaling contribute to SR-A1 mediated BMDM polarization in the glioma microenvironment." (PMID 27367025, 2016). "We treated two PN and two MES glioma spheres separately with inhibitors of Wnt signalling, CaMKII, TAK1, NF-κB, and STAT3." (PMID 27698350, 2016). "Based on our findings, we demonstrated that KIAA0247 suppressed glioma cell proliferation and angiogenesis and promoted apoptosis via inactivation of AKT and Stat3 signaling and their downstream targets." (PMID 27893430, 2016). "SR-A1 deletion promoted M2-like tumor-associated macrophage (TAM) polarization in mice by activating STAT3 and STAT6, which resulted in robust orthotopic glioma proliferation and angiogenesis." (PMID 27367025, 2016). "The expression of IL6, p-STAT3, HIF1A, and LC3B positively correlated with the WHO grade of glioma, and Pearson's or Spearman's rho rank correlation tests showed that IL6, p-STAT3, HIF1A, LC3B and grade were positively correlated." (PMID 27163161, 2016). "Mechanistically, overexpression of KIAA0247 is able to inhibit phosphorylation of AKT and Stat3 in glioma cells, resulting in inactivation of the AKT and Stat3 signaling pathways, this ultimately decreases the expression of PCNA, CyclinD1, Bcl2 and VEGF." (PMID 27893430, 2016). "A microarray expression analysis in mesenchymal gliomas found that expression of BHLHE40 and a number of other transcriptional regulators of mesenchymal transition including CEBPB, CEBPD, and STAT3 correlates with the extent of necrosis." (PMID 27096627, 2016). "IL6 and p-STAT3 levels correlated with the abundance of autophagic cells and HIF1A levels in human glioma tissues and with the grade of human glioma, whereas inhibition of exogenous or endogenous IL6 repressed autophagy in glioblastoma cells in vitro." (PMID 27163161, 2016). "Herein, we sought to determine the role of Suppressor of Cytokine Signaling 3 (SOCS3), a negative regulator of Signal Transducer and Activator of Transcription 3 (STAT3), in GAM functionality in glioma." (PMID 26967393, 2016). "High STAT3 and ANGPTL4 levels were observed in high-grade (GBM) samples in the TCGA database when compared to normal brain and low-grade glioma." (PMID 25955030, 2015). "STAT3 and ANGPTL4 expression was examined in 10 normal brain samples, 466 individual low-grade glioma patients and 328 individual high-grade (GBM) patients." (PMID 25955030, 2015). "After demonstrating that RTVP-1 is preferentially expressed in the mesenchymal subtype of GBM and is positively regulated by C/EBPβ and STAT3, we next examined if RTVP-1 plays a role in regulating the mesenchymal phenotype of glioma cells." (PMID 26267319, 2015). "From a mechanistic point of view, we suggest that STAT3 activation and the release of CXCL9/10 are suitable candidates to answer the question of how microglia supports glioma growth." (PMID 26157361, 2015). "Both STAT3 and ANGPTL4 expression is significantly increased in GBM samples when compared to normal tissue and low-grade gliomas." (PMID 25955030, 2015). "In this study, miRNAs and mRNAs were simultaneously profiled using high-throughput sequencing in human glioma cell lines after interfering with the expression of miR-181d, -21, and -23b, as well as β-catenin, CBP, and STAT3." (PMID 25007077, 2014).
glioma (continued). "Here, we examined paired deep sequencing expression profiles of miRNAs and mRNAs from human glioma cell lines after manipulating the levels of miRNAs miR-181d, -21, and -23b, as well as transcriptional regulators β-catenin, CBP, and STAT3." (PMID 25007077, 2014). "INPP5F deletion is correlated with a decreased survival rate for glioma patients, and overexpressed INPP5F suppresses glioblastoma cell proliferation, GSCs' self-renewal, and gliomagenesis through inhibition of STAT3 pathway." (PMID 25476455, 2014). "Increased STAT3 and focal adhesion kinase (FAK) has also been demonstrated in SOCS3 knockdown glioma cells leading to increased tumor invasion." (PMID 24518612, 2014). "In GL261 glioma cells, TNF-α-induced NF-κB activation was observed at 1 h, and STAT3 activation at 6 h." (PMID 24244348, 2013). "In cultured glioma cell lines as well as human GBM xenografts, we found that TNF-α treatment activated both the NF-κB and STAT3 pathways, in a temporal manner." (PMID 24244348, 2013). "When the STAT3 pathway is blocked in the setting of VEGF inhibition in mice with intracerebral gliomas, glioma volume is reduced and the additive effect correlated with inhibition of nestin and glioma-infiltrating macrophages." (PMID 23013619, 2012). "A subset of 7 transcription factors (STAT3, BHLHE40, CEBPA and B, RUNX1, FOSL2 and ZNF238) controlled most genes of the mesenchymal signature of gliomas; all but ZNF238 were significantly upregulated in the group 2 tumours compared to the other DIPG." (PMID 22389665, 2012). "Signal transducer and activator of transcription 3 (STAT3) is constitutively active in GBM and correlates positively with the glioma grades." (PMID 21906308, 2011). "We discovered that some targets of these microRNAs such as STAT3, PTBP1 or SIRT1 are differentially expressed in gliomas consistent with deregulation of microRNA expression." (PMID 21655185, 2011). "The roles these HCMV gene products play in dysregulating key pathways in glioma biology, including the PDGFR, AKT, STAT3, and monocyte/microglia function are discussed." (PMID 22030012, 2011). "C6 glioma differentiation was determined by morphological characterization, immunostaining and Western blot analysis on upregulation of GFAP and o p-STAT3 expression, and upregulation of intracellular cAMP." (PMID 21159181, 2010). "Because of insufficient patient numbers, no statistically meaningful conclusion can be drawn regarding differences in p-STAT-3 levels between newly diagnosed and recurrent grade III gliomas." (PMID 19900287, 2009). "Within the immune cells, γ-IFN has been shown to be down-regulated by p-STAT-3 and accordingly γ-IFN levels have been shown to be decreased in glioma patient PBMCs." (PMID 19900287, 2009). "Thus, the TRPC1-HDAC6 axis inhibits STAT3 degradation by suppressing CMA activity, contributing to glioma progression." (PMID 41787243, 2026). "In human glioma, TrkB.T1 has been found to enhance PDGF-driven gliomas in vivo, and in vitro experiments have revealed that TrkB.T1 augments the persistence of PI3K and STAT3 signaling pathways, including pAkt and pS6rp." (PMID 40133476, 2025). "We examined the role of GPM6B in glioma stem cells and found that GPM6B suppressed the sphere-forming capacity of GSCs, accompanied by reduced expression of Wnt pathway–related proteins, including β-catenin, p-STAT3, and c-Myc." (PMID 41450963, 2025). "Notably, IGFBP2 is an established oncogene in various tumors including myeloid leukemia, gliomas, breast, and prostate cancer, and orchestrates multiple cancer signaling pathways such as PI3K-AKT, NF-κB, and EGFR/STAT3." (PMID 40193528, 2025). "Glioma stem cells express high levels of TLR9, leading to STAT3 activation." (PMID 41157253, 2025). "Metformin may affect the behavior of glioma stem cells by activating AMPK and inhibiting the phosphorylation of mTOR and STAT3." (PMID 39944825, 2025).
glioma (continued). "In addition, MYC expression in glioma cells is induced by integrin α5β1-dependent JAK, and STAT3 activation, which follows, which in turn are regulated by stiff ECMs." (PMID 40124511, 2025). "Furthermore, overexpression of CSMD1 in glioma cell lines suppressed the aggressive phenotype and TNF/P65/IL-6 and IL-8/STAT3 pathways." (PMID 38561856, 2024). "In addition, we evaluated the correlation between the expression of the top 3 hub genes, STAT3, FOS and TLR4, in the grade 4 glioma tissue and model 1 miRNAs, miR-362-3p and miR-6721-5p, in serum." (PMID 38455766, 2024). "Consistent with miR-410 suppression of STAT3 in cultivated glioma cells, a significant negative correlation was detected between the mRNA levels of STAT3 and the levels of miR-410 in glioma samples (P < 0.001, r = -0.8865)." (PMID 38238515, 2024). "Gene set enrichment analysis (GSEA) revealed that several pathways, including JAK/STAT3 signaling, epithelial-mesenchymal transition, STAT5 signaling, NF-κB activation, and apoptosis, were differentially enriched in glioma samples with high LINC00324 expression." (PMID 38530810, 2024). "Notably, STAT3 overexpression rescued the influence of TCAF2 knockdown on migration/invasion, together with EMT-like processes, suggesting that TCAF2 promotes glioma cell migratory/invasive properties through activating STAT3 signaling." (PMID 38019450, 2024). "Taken together, our study reveals the miR-125a-STAT3 pathway through which exosomal NEAT1 from treatment-resistant GSCs contributes to M2-like macrophage polarization, indicating the potential of exosomal NEAT1 for treating glioma." (PMID 39061140, 2024). "Based on these findings, we speculate that the activation of the Wnt/β-catenin and JAK-2/STAT-3 signaling pathways by SRPK1 promotes the proliferation, migration, and invasion of gliomas." (PMID 38397980, 2024). "On the other hand, the activation of signaling pathways such as NFκB by TNF by microglia, astrocytes, or glioma cells themselves can induce an increase in IL6 expression, which can activate the JAK/STAT3 pathway and contribute to tumor proliferation, migration, and invasion." (PMID 38248305, 2024). "Furthermore, immunofluorescence assay showed that STAT3 was typically expressed in the cytoplasm of A172, LN428, and U251 glioma cells, but its expression decreased after treatment with BY4003 and BY4008." (PMID 39153914, 2024). "Similarly, the mRNA expression levels of STAT3, IL-6, and TNF-α, which are crucial factors in the STAT3 pathway, were elevated in glioma tissues compared to paracancerous tissues." (PMID 38495483, 2024). "In glioma, TFAP2A disturbs the expression of stemness-related genes, such as NANOG, SOX2 and CD133, via both directly binding the regulation region of NANOG and indirectly interfering with the IL6/JAK2/STAT3 signaling pathway." (PMID 37291585, 2023). "Furthermore, TMEM158 positively correlates with STAT3 signaling in glioma cells, and regulates the glioma cell proliferation, migration, invasion, and EMT process by activating STAT3 signaling." (PMID 37936608, 2023). "In addition, gliomas release immunosuppressant cytokines such as TGF-β, IL-10 and cyclooxygenase 2 (COX-2), while simultaneously inhibiting signal transducer and activator of transcription 3 (STAT3), thus enhancing the immunosuppressive microenvironment." (PMID 37686020, 2023). "Similarly, the expression of both STAT3 and FOXM1 was shown to be concurrent following radiation treatment in high-grade gliomas." (PMID 37821870, 2023). "Given the findings that GDF15 is required for the activation of STAT3 and tumorigenesis in thyroid cancer and glioma stem cells, we focused whether GDF15 function is mediated through STAT3 signaling in gastric cancer cells." (PMID 36769245, 2023). "Gliomas with high TANK levels exhibited enrichment in immunomodulatory pathways, including “hypoxia”, “angiogenesis”, “inflammatory response”, “NF-kappaB signaling”, and “IL6/STAT3 signaling” in the TCGA cohort." (PMID 37215097, 2023).
glioma (continued). "The chromatin at the LIF locus exhibited a conformation consistent with active transcription, LIF mRNA was increased, and phosphorylated Stat3 (pStat3) was increased, which supported the upregulation of the LIF and the downstream JAK/STAT pathway in H3.3-G34R/V mutant gliomas." (PMID 37509641, 2023). "Our findings suggest that in SHH medulloblastoma, as in glioma, IGFBP2 may regulate a STAT3-mediated EMT program in order to drive metastasis." (PMID 37029430, 2023). "Signal transducer and activator of transcription 3 (STAT3), which could be activated by HCMV infection, plays important roles in glioma mesenchymal phenotype, angiogenesis, cell survival, and immune- suppression/immune evasion." (PMID 37424781, 2023). "Non-neoplastic astrocytes also contribute to glioma progression by expressing tumor-promoting proteins such as TGF-ß, STAT3, CCL2 and CSF1 in later tumor stages after causing initial astrogliosis at the tumor boundary in earlier tumor stages." (PMID 38275375, 2023). "The results revealed that p-STAT3 was significantly increased in TMEM158- overexpressing glioma cells, whereas total STAT3 levels did not vary significantly from that of β-actin." (PMID 34992215, 2022). "Moreover, ZEB1, CA9, HSPB1, STAT3 and TNFAIP3 of the overlapping genes were upregulated in glioma tissues." (PMID 35711838, 2022). "However, reduced p-STAT3 levels were further observed in U87MG, U251MG, and TJ905 glioma cells in response to TMEM158 downregulation." (PMID 34992215, 2022). "In the glioma cells, the EGFR signaling pathway was decreased via reduction of the STAT3, ERK, and AKT cascade, while iPA inhibited the farnesyl diphosphate synthase (FDPS) activity via reduction of protein prenylation, thus arresting the proliferation of thyroid cancer cells." (PMID 36551529, 2022). "In summary, this study demonstrated that paeoniflorin might function as an effective drug for glioma by inducing ferroptosis via upregulation of NEDD4L and repression of Nrl2, GPX4, and STAT3." (PMID 36618071, 2022). "TNFα can facilitate angiogenesis by increasing epidermal growth factor receptor (EGFR) activity; it induces immune cell suppression through the activation of the NF-κB and STAT3 pathways, and decreases the expression of the tumor-suppressor gene PTEN in glioma." (PMID 35626018, 2022). "Moreover, the JAK/STAT3 and TNFA/NFKB pathways were also enriched with high GSVA scores in AC-like glioma cells at the single-cell level." (PMID 36429098, 2022). "Given the relevance and frequency of ATRX mutations in high-grade glioma patients, we sought to validate the effect of BTK, STAT3, and RTK inhibitors in glioma cell lines derived from adult malignant glioma (MOG-G-UVW and U-251) and pediatric malignant glioma (SF188) patients." (PMID 35406561, 2022). "Thus, the STAT3-dependent (as well as SOX2- and TCF3-dependent) increase in ERRFI1 expression provides the common glioma path for the regulation of EGFR signaling." (PMID 36231068, 2022). "In glioblastoma, BMX non-receptor tyrosine kinase is overexpressed, promoting the abnormal activation of the signal transducer and activator of transcription 3 (STAT3), which is involved in self-renewal of glioma stem cells (GSCs) and maintaining GSC tumorigenic potential." (PMID 35954371, 2022). "Regardless of the mechanism behind its activation, STAT3 undoubtedly possesses a crucial part in the pathogenesis of gliomas, the proliferation and migration of glioma cells, while contributing to the stem-like phenotype, angiogenesis, and immune suppression." (PMID 35409080, 2022). "Finally, we highlight the intimate link between high STAT3 signaling, E2F1 and H2AZ2 expression in glioma patients." (PMID 35058574, 2022). "MiR-33a may exert oncogenic effects by regulating JAK2/STAT3, cAMP/PKA, and NOTCH signaling pathways in gliomas." (PMID 36061185, 2022).
glioma (continued). "These genes include HMGA1 in glioma, AKT1 in glioma, PTC, GC, and HCC, HEMGN in PTC, APLN and MMP19 in GC, WNT1 in CRC, NUPR1 in CRC and OSCC, LY6E and CTSB in CHOL, KLK4 and PLXNB2 in OC, and HDAC4 and STAT3 in SaOS." (PMID 36175921, 2022). "Depletion of STAT3 reversed KAT6B-regulated viability, apoptosis, and ferroptosis of glioma cells." (PMID 35432536, 2022). "Additionally, it has been observed to promote glioma growth and invasion via mTOR signalling and to promote malignant progression by attenuating the miR-384/PIWIL4/STAT3 axis, in accordance with our results." (PMID 35311131, 2022). "The STAT3 inhibitor, NAP, can remarkably suppress the glioma growth and invasion and could thus be a potential strategy for treating glioma." (PMID 36741734, 2022). "In addition, some studies have pointed out that the JAK2/STAT3 pathway can act as an upstream immune signal to regulate the PI3K/AKT pathway and affect the therapeutic effect of glioma." (PMID 36065261, 2022). "As a result of dysregulated upstream events and a lack of negative STAT3 regulation, STAT3 has been shown to be constitutively activated in glioma." (PMID 34276757, 2021). "This suggests that among the TFs previously characterized (such as FOSL2, STAT3, BHLHB2, and RUNX1), FOSL1 and CEBPB might play a dominant role in the NF1-mediated MES transition that occurs in a glioma cell-intrinsic manner." (PMID 34399888, 2021). "Meanwhile, STAT3 boosted LINC00662 transcription, which indicates that LINC00662 may be exploited as a molecular marker and therapeutic target for gliomas." (PMID 37305396, 2021). "Activated NF-κB can mediate the activation of STAT3, CEBPB, and TAZ by upregulating the expression of CD44, vimentin, and N-cadherin, thereby promoting the invasion, angiogenesis, and therapeutic resistance of glioma." (PMID 34246306, 2021). "Based on above results, we speculated that ELK3 overexpression might promote the malignant growth, proliferation, and migration of gliomas through regulating expression of JAK2 and STAT3, especially STAT3." (PMID 34976781, 2021). "Considering the observed overactivation of JAK2/STAT3 in glioma, we speculated that fraxetin might have an inhibitory effect on glioma development via suppressing JAK2/STAT3 activity." (PMID 33959183, 2021). "In addition, immunohistochemistry of intracranial glioma tissues further confirmed that CYB561D2 increased PD-L1, MMP2 (invasion marker) and Ki-67 (proliferation marker) in a STAT3-depedendt manner." (PMID 34372858, 2021). "We found that inhibition of STAT3 with WP-1006 enhanced the mitochondrial depolarization and AIF translocation from mitochondria to nuclei induced by the combination of sorafenib and TMZ in U251 glioma cells." (PMID 34277607, 2021). "We found that SD‐36, but not Stattic, decreased STAT3 levels in the examined glioma cell lines; these events occurred very rapidly even at 1 hour post‐treatment." (PMID 34291563, 2021). "FAK phosphorylation was reported to promote STAT3 activation and MMP-2 activity in gliomas." (PMID 33428595, 2021). "As previously reported, STAT3 regulates ARG1 in MDSCs from cancer patients, and in our study, we found that its quantity and activity are significantly increased in the blood of glioma patients, in line with a previous work." (PMID 35069595, 2021). "In normal cells, the activation of STAT3 is transient, but in gliomas, due to the lack of upstream regulatory signals and negative regulatory mechanisms, STAT3 is constitutively highly expressed and activated." (PMID 34425834, 2021). "These experimental results demonstrated that JAK2/STAT3 signaling was involved in the EMT process of glioma cells and suggested that the inhibitory effect of NC on glioma EMT may be achieved via the JAK2/STAT3 pathway." (PMID 33788424, 2021). "Taken together, these results further confirm that CYB561D2 up-regulation activates STAT3 in gliomas and CYB561D2-activated STAT3 might modulate target gene expression to regulate tumor behaviors." (PMID 34372858, 2021).